TNF (tumor necrosis factor)
Diseases named in the same sentence as TNF in open-access papers (continued):
Sharing a sentence is not in itself a finding about the gene and the disease.
colitis (continued). "As expected, colitis mice treated with Bp7 and Bp8 exhibited lower concentrations of TNF-α and IL-1β (p < 0.05) and higher concentrations of IL-10 and IL-22 relative to the DSS group (p < 0.05)." (PMID 35681301, 2022). "In TNBS-induced colitis, the increased TNF-α immunoreactivity in colonic tissue was significantly reduced by anti-inflammatory treatments in rats." (PMID 35239781, 2022). "In conclusion, our results suggest that, during acute colitis, the release of pro-inflammatory mediators, such as TNF-α, increases the excitability of DRG sensory neurons whose peripheral nerve endings innervate the colon." (PMID 36032155, 2022). "The mRNA and protein levels of IL-1β, TNF-α, and NF-κB/p65 in colonic tissue from the colitis mice were decreased after the STV-Na treatment." (PMID 35126813, 2022). "Transcript levels of IL-6, IL-1β, and TNF-α were considerably higher in both colitis groups in this investigation." (PMID 35054518, 2022). "Some of these strains ameliorate colitis in mice and rats and reduce the expression of TNF-α and IL-17 in UC patients biopsies." (PMID 36687706, 2022). "Our consequences displayed that anethole considerably decreased the level of MDA, increased the TAC, and decreased the gene expression of inflammatory cytokines including TLR4, TNF-α and IL-1β in the colon tissue of the colitis group." (PMID 35432569, 2022). "The DSS-induced colitis mouse model is primarily a macrophage/Th1/Th17 driven inflammatory model with increased levels of pro-inflammatory cytokines such as TNF-α, IL-1β and IL-6." (PMID 36365201, 2022). "TNF-specific antagonist reduces the number and size of tumors in the AOM/DSS model and limits the risk of colitis-associated CRC." (PMID 35884974, 2022). "To further estimate the influence of MOP upon inflammation in colitis, we detected the levels of TNF-α, IL-1β, IL-6, and IL-10 in the serum from the control, DSS, and DSS + H MOP groups." (PMID 35911761, 2022). "There is a significant increase in IL-1β and IL-6 mRNA expression in the cortex and IL-1β and TNF-α in the hippocampus of mice with DSS-induced colitis." (PMID 34983592, 2022). "It is also found that green tea extract effectively alleviated the inflammatory response in IL-2-deficient mice, inhibited the overproduction of TNF-α and IFN-γ, and reduced the incidence of severe colitis." (PMID 35205982, 2022). "Secondly, the administration of JW markedly inhibited the neutrophil infiltration and CASP3-dependent inflammation-promoting pyroptosis in murine colitis models and suppressed TNFα-induced ROS production in IOs." (PMID 36091591, 2022). "In an animal study, administration of F. prausnitzii to trinitrobenzene sulphonic acid-induced colitis mice reduced the severity of colitis, with increasing IL-10 secretion and decreasing TNF-α and IL-12 secretion in the colon." (PMID 35163104, 2022). "Pathogenic bacteria of colitis such as Shigella, Oscillospira and Xenorhabdus, which were negatively correlated with most SCFAs, were significantly positively correlated with MPO, TNF-α, IL-1β, IL-6, IL-17, and IgE (P ≤ 0.05)." (PMID 36451737, 2022). "To further assess the effect of LBGH on DSS-induced colitis in mice, we measured the levels of pro-inflammatory cytokines including IL-1β, IL-6, and TNF-α in serum as well as in colonic tissue through ELISA kits." (PMID 36033869, 2022). "In this study, the IL-1β and TNF-α levels were much higher in the DSS-induced colitis mice in contrast to control mice." (PMID 35126813, 2022). "The deficiency of CXCL13 resulted in significantly decreased expression of inflammatory cytokines IL-21, IL-1β, IL-1α, IL-17, IL-6 and TNF-α in colon sites of mice with colitis." (PMID 36172372, 2022). "For example, fermented millet bran can significantly reduce serum pro-inflammatory cytokines TNF-α and IL-6, thus improving recurrent colitis, and has a significant protective effect on colonic inflammation." (PMID 35885325, 2022).
colitis (continued). "In both colitis models, the olive extract reduced the expression of proinflammatory mediators (IL-1β, TNF-α, and iNOS) and improved the intestinal epithelial barrier by restoring the expression of ZO-1, MUC-2, and TFF-3." (PMID 35215407, 2022). "Consistent with this, blood T cells during colitis expressed TNF on their surface as detected by flow cytometry, but did not produce increased IL-22BP levels when compared to WT controls." (PMID 35383266, 2022). "Another approach of L. lactis bioengineering was created to counteract the increased TNF-α release during colitis." (PMID 35628274, 2022). "Inconsistent with the results of our study, two studies showed Clostridium butyricum reduced colitis-associated CRC on AOM/DSS murine models and decreased proinflammatory cytokines TNF-α, IL-6, and COX-2, and increased anti-inflammatory cytokine IL-10." (PMID 36077084, 2022). "Natural polyphenols from plants, such as curcumin, mangiferin, and catechin, have demonstrated anti-inflammatory effects in TNBS/DSS-induced colitis models and reduced TNF-α expression." (PMID 36145301, 2022). "A recent study reported that TNF‐α increased macrophage expression of phosphatase Shp2, which exacerbated colitis by desensitizing macrophages to the anti‐inflammatory function of IL‐10." (PMID 35593111, 2022). "Thiopurines, biological agents that target tumor necrosis factor and integrins, as well as small-molecule Janus kinase inhibitors, are among the drug classes used to treat mild to severe colitis." (PMID 36358470, 2022). "The pharmacological evaluation showed that FMPs attenuated inflammation in AA-induced colitis by reducing the serum concentrations of TNF-α, IL-6, IL-8, and IL-10 and the colonic concentrations of MPO, MMP9, and CXCR1." (PMID 35620404, 2022). "NF-κB mediated the production of various proinflammatory cytokines, such as IL-6, TNFα, and IL-1β, which regulated inflammatory responses in colitis induced by DSS (M. L. Chen and Sundrud 2016; Neurath 2014; Fantini and Pallone 2008)." (PMID 35433693, 2022). "Our studies have shown an attenuation of colonic markers of inflammation (e.g., TNF-α) and a significant improvement of chemical-induced colitis in FAT-1 mice with elevated n-3 PUFA levels." (PMID 35628140, 2022). "Higher levels of pro-inflammatory cytokines including TNF-α, IL-1β, and IL-6 and lower levels of anti-inflammatory cytokine IL-10 were found in colitis mice when compared with the control group." (PMID 35911761, 2022). "There was an increase in TNF levels in the hippocampus of vehicle-treated colitis mice compared with the naive group (p < 0.05)." (PMID 35295931, 2022). "Mechanistically, overexpression of PFKFB3 induced phospho-p65 and promoted the expression of IL-1β and tumor necrosis factor alpha (TNF-α) in the development of colitis and CAC." (PMID 36016583, 2022). "Our prior findings in Mttp-IKO mice demonstrated increased circulating levels of TNFα and exaggerated colonic inflammation and injury during experimental colitis." (PMID 34563519, 2021). "Consistently, activated FcγR-deprived mice fail to effectively response to anti-TNF therapy in T-cell transfer colitis model, while administration of anti-TNF monoclonal antibodies with enhanced Fc-binding affinity shows improved efficacy." (PMID 35692862, 2021). "It was recently established that loganin at the doses of 80 and 160 mg/kg and morroniside at the doses of 90 and 180 mg/kg significantly decreased the expression of IL-1β and TNF-α in colon tissues of mice with dextran sodium sulfate-induced colitis." (PMID 34834710, 2021). "In the present study, OF.Cr treatment resulted in significantly decreased release of TNF-α and IL-6, as compared with the AA-induced colitis rats." (PMID 33802553, 2021). "The levels of TNF-α, IL-1β, and IL-6 in colon tissues of colitis mice were elevated by contrast with those in the Model group." (PMID 34055024, 2021).
colitis (continued). "In a colitis model, the authors demonstrated that the loss of the ODC gene leads to pronounced induction of inflammatory cytokines including GM-CSF, TNF-α, IL-1α and IL-1β, and IFN-γ as well increased macrophage polarization towards M1." (PMID 34206987, 2021). "On the other hand, we observed significant reduction in TNFα expression in the gut on day 5 of DSS colitis and a similar trend for IL-6." (PMID 33986741, 2021). "A deeper analysis identified the downregulation of GM-CSF/M-CSF, IL-6, and TNF-α and the inhibition of the NF-κB/IL-6/STAT3 pathway as further contributors to colitis-associated cancer." (PMID 34950252, 2021). "The TNF-α-treated Caco-2 cell model and mouse colitis model induced by dextran sulfate sodium (DSS) or 2,4,6-trinitrobenzenesulfonic acid (TNBS) are well-established models for UC investigation." (PMID 33776781, 2021). "The mucosal immune system is activated during colitis, which is accompanied by increasing mRNA expression of pro-inflammatory cytokines, including tumor necrosis factor (TNF)-α, interleukin (IL)-1β, and IL-6." (PMID 34867926, 2021). "After mice with TNBS-induced colitis were treated by intragastric administration of ginsenoside Rb1, the levels of pro-inflammatory cytokines (TNF-α, IL-1β, and IL-6) declined, while the levels of anti-inflammatory cytokines (IL-10) increased." (PMID 33462754, 2021). "We found that treatment of both L.L-pMU45CR and L.L-pNU45CR reduced IL-6, IL-1β, and TNF-α expression, and restored IL-10 production which plays a regulatory role in colitis." (PMID 34650393, 2021). "The level of IL-1β, IL-6, and TNF-α in the colon samples were found to be increased in response to the induction of colitis in mice, whereas, significantly reduced (p < .01) after CD–Cur–CANPs treatment." (PMID 34121560, 2021). "It was shown that upon CIN-102 treatment, decreased mRNA levels of the pro-inflammatory cytokines IL-1β and TNF-α and increased expression of IL-6 was noted in colonic tissue in mice suffering from colitis." (PMID 34106933, 2021). "High levels of pro-inflammatory cytokines, such as TNF-α, IL-1β, and IL-12, are associated with DSS-induced colitis in mice." (PMID 34899643, 2021). "Lactobacillus johnsonii and Lactobacillus paracasei PS23 increase hippocampal TNF-α expression in mice with Escherichia coli-induced colitis and with age-dependent cognitive decline, respectively." (PMID 34667205, 2021). "Animals with colitis administered with RL-FNPs expressively reduced the expression of TNF-α, IL-1β, IL-6, and IL-12, with effectiveness comparable to that of the dexamethasone group, with the exception of IL-12." (PMID 33499333, 2021). "Results from ELISA confirmed that chrysophanol suppressed the production of serum TNFα and IL-6 in the colitis model." (PMID 33802855, 2021). "Surprisingly, colonic TNF-α levels were increased in curdlan-fed mice compared to vehicle-fed mice under non-colitis conditions." (PMID 33920960, 2021). "Some proinflammatory cytokines and mediators (e.g., TNF-a, IL-6 and IL-1β) have been used as markers of anti-inflammatory activity in a dextran sodium sulfate colitis mouse model, and IL-10 has anti-inflammatory properties and functions in immune regulation." (PMID 34490398, 2021). "After MSC-Exo treatment, the colon length in colitis mice increased; colon inflammatory injury decreased; TNF-α, IL-6, IL-1β, IL-17, and IL-18 levels decreased; and Claudin-1, ZO-1, and IκB levels increased." (PMID 34249964, 2021). "ELISA data showed that the expression levels of TNF-α, IL-1α, IL-6, and IL-8 in colitis mice were significantly reduced compared with those in control samples." (PMID 34456974, 2021). "To understand the role of Lgals3bp in inflammatory responses during colitis, we measured the expression of pro-inflammatory cytokines, such as IL-6, TNF-α, and IL-β using RT-qPCR." (PMID 33824294, 2021).
colitis (continued). "In an experimental model of intestinal inflammation, such as dextran sulfate sodium (DSS)-induced colitis, an incremental increase in colitis severity was observed in mice after monoclonal anti-TNF administration." (PMID 34638616, 2021). "Reducing TNF-α and IL-6 in mice with colitis was considered to be a logical target for the treatment of colitis." (PMID 34195297, 2021). "In this study, LD4-PDT treatment significantly inhibited TNF-α, IL-1 and IL-6 expression, and consequently reduced the severity of colitis in UC model." (PMID 34744725, 2021). "Lactic acid and SyBE also significantly reduced the contents of pro-inflammatory cytokines, such as TNF-α, IL-6, and IL-1β, in serum, that promote the development of colitis." (PMID 34899735, 2021). "It was shown that oral administration of CUR-SBLNs reduced the infiltration, oxidative stress, and secretion of TNF-α in a DSS-induced colitis model." (PMID 33918207, 2021). "DSS-induced colitis mice showed significant decreases in spleen and thymus indices; NK cytotoxicity; and TNF-α, IFN-γ, and IL-2 concentrations in serum." (PMID 33562018, 2021). "In accordance with other studies, we showed that colitis induction resulted in a significant increase in the level of proinflammatory cytokines (IL-1β, TNF-α, IL-6, and IFN-γ) and decreased the anti-inflammatory cytokine IL-10 in colon tissue." (PMID 33995942, 2021). "Previous studies described that inflammation of the colon increases the activity of inflammation-related cytokines including TNF-α, IL-1β, and IL-6 in serum and colon tissues in murine colitis." (PMID 34066160, 2021). "ER stress plays a key role in human diseases, including colitis and acute pancreatitis, by increasing the release of proinflammatory factors such as IL-1β, cleaved caspase-1, and TNF-α which is elicited by TXNIP during neuroinflammation." (PMID 34790063, 2021). "In the inflammatory phase of DSS-induced colitis, IL-1β, TNF-α and IL-6 mRNA expression were significantly increased in the colon." (PMID 34749758, 2021). "In according with this findings, the anti-inflammatory effects of RA, mediated by reduction of TNF-α release, have been previously reported in experimental colitis." (PMID 33530569, 2021). "FAMB significantly promoted the lymphocyte proliferation and natural killer (NK) cell killing activity in colitis mice, and increased the concentrations of TNF-α, IFN-γ, and IL-2 in serum." (PMID 33562018, 2021). "In turn, increased TNF-α aggravates colitis by activating more macrophages, recruiting neutrophils into the site of inflammation and stimulating edema." (PMID 33946346, 2021). "This study showed that B. persicum essential oil significantly reduced the high level of TNF-α in the colon tissue of acetic acid-induced colitis." (PMID 34745922, 2021). "Vimang, a stem bark extract of the mango, also showed anti-inflammatory activity through the inhibition of PGE2, TNF, and nitric oxide (NO) in the experimental colitis model, in vivo and in vitro." (PMID 34066494, 2021). "The colitis model group expressed significantly higher levels of colonic TNF-α, IL-1β, and IL-6, and lower levels of IL-10 compared with the control group." (PMID 35071260, 2021). "The spontaneous colitis phenotype was largely dependent on TNF-α induced apoptosis of colonic epithelial cells." (PMID 34956195, 2021). "Oral administration of PCA improved symptoms of DSS-induced colitis in rats and prevented the increase in the pro-inflammatory cytokines IL-1β, IL-6, and TNF-α that was seen in controls." (PMID 34073220, 2021). "They designed NPs with a Fab’ portion of the F4/80 antibody against murine macrophages, which also contained TNFα-siRNA showing high efficiency in the attenuation of colitis." (PMID 34575416, 2021). "Colitis also induced a significant increase in the colonic levels of the pro-inflammatory cytokines TNF-α, IFN-γ, IL-1β, IL-6 and IL-17 measured via CBA." (PMID 34248633, 2021).
colitis (continued). "Our experiments show that neuroinflammation and neuronal hyperexcitability develop in all three colitis models as a consequence of TNFα-secreting neutrophils that infiltrate the brain." (PMID 34511110, 2021). "Current management for ICI-colitis includes systemic corticosteroids and subsequent anti-TNFα therapy (infliximab) for inadequately controlled disease." (PMID 34147519, 2021). "While our data point to important roles of neutrophils and TNFα in colitis-induced neuroexcitability, other cells and inflammatory mediators likely also contribute." (PMID 34511110, 2021). "Oat β-glucan was shown to prevent DSS-induced colitis by downregulating the levels of TNF-α, IL-1β, IL-6, and iNOS." (PMID 35008842, 2021). "In agreement with previous studies, we observed that systemic GSK-J4 administration induced a reduction in the production of TNFα by macrophages upon DSS-induced colitis." (PMID 33446666, 2021). "Two different studies have shown that FXR activation reduces the differentiation and activation of intestinal DCs by down-regulating TNF-α expression and alleviating the severity of colitis in mouse models." (PMID 34064187, 2021). "On the contrary, IFN-γ, IL-17, TNF-α, and IL-6 are pro-inflammatory factors usually strongly exacerbating the inflammation cascade in colitis." (PMID 34090510, 2021). "The results showed that rTsSp pre-treatment reduced the colon tissue TNF-α expression of mice with DSS induced colitis." (PMID 33995396, 2021). "Taken together, the TNF-α siRNA-loaded PPADT NPs effectively silenced TNF-α expression in mice suffering from colitis." (PMID 35052764, 2021). "In the next phase of the in vitro studies, we used cells of intestinal epithelial origin (Caco-2) and mimicked the conditions that occur in the intestinal microenvironment during colitis by addition of TNFα, IL1-β, INFγ, and LPS." (PMID 34444876, 2021). "The knock-down of miR-155 protects the experimental colitis mice by decreasing IFNγ, TNFα, IL-6, IL-12 and IL-17 production, reducing Th1 response and suppressing the T-cells activation by DCs." (PMID 33921348, 2021). "FAHF-2 suppressed TNF-α production by human peripheral blood mononuclear cells (PBMCs) and colonic mucosa, and abrogated colitis in a murine model." (PMID 34926527, 2021). "TNBS-induced acute colitis maintains many pathological features of human colitis, especially increasing type I inflammatory response and helper T cell 1 (Th1)-related cytokines, such as TNF-α or interferon-γ (IFN-γ)." (PMID 33461587, 2021). "Nevertheless, microbial dysbiosis (regardless of the pattern) provoked similar immune response with an obvious increase in IL-23 and IL-17, as well as IL-1, IFN-γ, and TNF-α cytokines coinciding with colitis as early as 2 months of age in the various strains." (PMID 34267743, 2021). "Our group already showed that type 1 cytokines, namely TNF, directly induce intestinal GC synthesis to ameliorate colitis while type 2 immune response in the model of oxazolone-induced acute colitis did not trigger GC synthesis due to the lack of TNF." (PMID 34012456, 2021). "Perez-Ruiz et al37 reported the therapeutic effect of TNF-α blockade against ICI induced-colitis in tumour-bearing mouse models." (PMID 34158547, 2021). "For example, in DSS-induced colitis, TpH1−/− mice produce lower levels of the pro-inflammatory cytokines TNF-α, IL-1β, and IL-6 and have reduced macrophage infiltration when compared to TpH1+/+ mice." (PMID 34502396, 2021). "Exposure to IS significantly induced colon shortening, myeloperoxidase activity, IL-1β, IL-6, and TNF-α expression, and NF-κB+/CD11c+ cell population in the colon, resulting in colitis." (PMID 33731795, 2021). "It has been reported earlier that, in colitis, increased levels of cytokines such as TNF-α and IL-6 have a significant contribution to body weight reduction by the release of appetite suppressive neuropeptides." (PMID 33802553, 2021).